MMP7 (matrix metallopeptidase 7)
Diseases named in the same sentence as MMP7 in open-access papers (continued):
Sharing a sentence is not in itself a finding about the gene and the disease.
atherosclerosis (17 papers, 2014 to 2025). A disease characterized by the build-up of fatty material and calcium deposition in the arterial wall resulting in partial or complete occlusion of the arterial lumen. "In patients with type 2 diabetes (TDM2), which is a risk factor of atherosclerosis and elevates the risk of stroke in patients with AF, MMP-7 and MMP-12 plasma levels were increased in comparison with patients without glucose metabolism disturbances." (PMID 36835040, 2023). "V55 reduced expression of Icam-1, Wnt5a and Mmp7 (associated to inflammation and tissue destruction in periodontitis) and Scd1, Scd2, Egf1 (correlated to atherosclerosis)." (PMID 35631379, 2022). "There is a paucity of data evaluating the association of the levels of MMP-7 with clinical manifestations of atherosclerosis." (PMID 30934954, 2019). "However, an intriguing correlation between MMP-7 and atherosclerosis-related blood lipids and neutrophil-associated inflammatory biomarkers seems to be disrupted by atorvastatin independently of hsCRP, possibly via pleiotropic effects." (PMID 39200884, 2024). "In atherosclerosis, MMP-7 has been linked to apoptosis of vascular SMC." (PMID 24400123, 2014). "V55 diminished the expression of Icam-1, Egfr, Wnt5a and Mmp7 (related to inflammation and tissue damage in periodontal disease) and Scd1, Scd2, Egf1 (related to atherosclerosis)." (PMID 35631379, 2022). "In fact, MMP-7 is also related to the development of hyperlipidaemia and atherosclerosis through its cleavage of lipid-free apolipoprotein A-IV, an event that plays an important role in lipid metabolism and oxidant activity." (PMID 32101136, 2020). "MMP-7 together with other MMPs has previously shown to be elevated in patients with atherosclerosis." (PMID 24400123, 2014). "Several studies suggest the involvement of MMP-7 in atherosclerosis." (PMID 39200884, 2024). "However, in light of the study’s findings, this section will focus on the relationship between MMP-7 and atherosclerosis." (PMID 39200884, 2024). "The atherosclerosis burden was decreased in Mmp-7 and Mmp-12 knockout animals but enhanced in Timp-1-devoid animals, as well as the degree of coronary arteries stenosis, whereas post-infarction cardiac fibrosis was increased in Mmp-7 as and markedly reduced in Timp-1-deficient mice." (PMID 36835040, 2023). "In the same year, MMP-7 has been reported to link to human atherosclerosis." (PMID 31752174, 2019). "MMP-7 seemed primarily a marker of atherosclerosis, but was influenced by smoking and age." (PMID 30789935, 2019). "To further elucidate the role of MMP-7 in atherosclerosis and plaque destabilization, we examined MMP-7 levels in patients with carotid plaque in relation to symptomatology, both systemically and within the lesion, and plasma levels of MMP-7 were also related to mortality during follow-up." (PMID 24400123, 2014). "Consequently, even in healthy individuals, statins might modulate the interplay between MMP-7 and biomarkers related to atherosclerosis." (PMID 39200884, 2024). "Plasma MMP-7 concentration might be a marker of atherosclerosis." (PMID 37759829, 2023). "However, at present, there are relatively few studies on MMP-7 in clinical atherosclerosis." (PMID 24400123, 2014). "In atherosclerosis, CXCL4 drives the differentiation of M4 macrophages, which co-express CD68, MMP7, and S100A8." (PMID 39707183, 2024). "These included proteins involved in atherosclerosis/inflammation (e.g. GDF-15, lipopolysaccharide binding protein, and CD14), extracellular matrix [matrix metalloproteinase-7 (MMP7)], heart failure [N-terminal pro-B-type natriuretic peptide (NT-proBNP)], and renal insufficiency cystatin C (CST3)." (PMID 39660078, 2024). "Therefore, we investigated two therapeutic strategies, which we have previously shown to reduce VSMC apoptosis in vitro and in the Apoe−/− mouse model of atherosclerosis: EC4-Fc (truncated N-cadherin) over-expression and Mmp-7 deletion." (PMID 29229950, 2017).
atherosclerosis (continued). "An increased circulating concentration of MMP7 and MMP12 may indicate active extracellular matrix remodeling that is involved in degrading the elastic layers and/or cell membranes basement with promotion of initiation and progression of atherosclerosis." (PMID 40272732, 2025). "The absence of a correlation between MMP levels and 18F-FDG uptake in the carotid arteries, aortic arch or abdominal aorta suggests that high plasma level of MMP-7 may reflect the atherosclerosis burden but does not inform about the presence of plaque inflammation in a specific vascular territory." (PMID 32101136, 2020).
interstitial lung disease (17 papers, 2007 to 2026). A diverse group of lung diseases that affect the lung parenchyma. "Serum matrix metalloproteinase-7 (MMP-7) has emerged as a reproducible indicator of fibrotic progression in interstitial lung disease, with concentrations above 3.53 ng/mL associated with increased risk of progression and an adjusted odds ratio of approximately 1.26 for fibrotic worsening." (PMID 41301796, 2025). "Krebs von den Lungen-6 (KL-6) and matrix metalloproteinase-7 (MMP7) are established serum biomarkers for interstitial lung disease (ILD)." (PMID 41049336, 2025). "Another study indicated that MMP7 was over-expressed in patients with subclinical interstitial lung disease and under-expressed in patients with mature IPF compared to healthy controls." (PMID 36936416, 2023). "In humans, serum MMP‐7 is considered potentially valuable for detection of subclinical interstitial lung disease." (PMID 33274549, 2021). "In particular, MMP-7 was correlated with disease severity and was higher in patients with subclinical interstitial lung disease (ILD), although it must be pointed out that Rosas’ results were obtained in a case series that did not include NSIP." (PMID 24336111, 2013). "A prospective cohort study evaluated the association of plasma matrix metalloproteinases (MMPs) with the incidence of interstitial lung disease in patients with rheumatoid arthritis in a large multicenter RA cohort, further supporting the potential pathogenic role of MMP-7 and MMP-9 for RA–ILD." (PMID 38808332, 2024). "Studies of humans have identified increased total MMP‐7 (including both pro‐form and active form) concentrations in the blood of IPF patients when compared with healthy controls, patients with other interstitial lung diseases, or those with chronic obstructive pulmonary disease." (PMID 33274549, 2021). "Recently, a biomarker index of SP-D, MMP-7, and osteopontin was found to enhance diagnostic accuracy in IPF patients compared to those with non-IPF interstitial lung diseases." (PMID 27977812, 2016). "MMP-7 (matrilysin), a metalloproteinase which targets a broad range of extracellular matrix proteins, was originally found to be highly overexpressed in IPF lungs and subsequently in other interstitial lung diseases." (PMID 22988462, 2012).
bladder cancer (16 papers, 2006 to 2024). "There were 7 associations graded as moderate associations for cancer risk, including MMP-2 rs243865 with LC risk and PCa risk, MMP-7 rs11568818 with bladder cancer risk, and MMP-9 rs3918242 with BC risk and oral cancer risk." (PMID 35574300, 2022). "Furthermore, compared with previous studies, our study included more studies and variants, and then it was revealed that MMP-2 rs243865 was associated with NPC and PCa risk, and MMP-7 rs11568818 with bladder cancer, CC, and CRC risk." (PMID 35574300, 2022). "Interestingly, we upgraded the associations (MMP-7 rs11568818 and CC among the Asian populations in the allelic model and bladder cancer among the overall populations in the recessive model) from moderate to strong." (PMID 35574300, 2022). "Moreover, MMP-7 plasma levels are significantly higher in patients with bladder cancer at high risk of diseases progression." (PMID 25984271, 2014). "For example, SLC12A5 can interact with and enhance SOX18 activity to promote bladder cancer progression via the NF‐κB/MMP‐7 pathway." (PMID 36645171, 2023). "Among these, NOTCH1, CCND1, CD44, MMP7, TGFR2, and FGFR3 are involved in bladder cancer signaling pathways or are associated with the development of bladder carcinoma." (PMID 33535616, 2021). "The serum matrix metalloproteinase-7 level (MMP7) assessment showed a significant correlation with nodal metastases in patients with bladder cancer with sensitivity and specificity of 82% and 71%, respectively, at serum concentrations 7.15 ng/mL." (PMID 33922894, 2021). "In urinary bladder cancer, circulating MMP-7 is a stage- and grade-independent prognostic factor of DSS and OS, wherein patients with high MMP-7 concentrations have a poor prognosis." (PMID 30678058, 2019). "Previous studies have reported elevated MMP-7 concentration in urine samples and also in plasma samples from patients with bladder cancer." (PMID 25984271, 2014). "In this study, we assessed with an immunoassay we developed, the prognostic value of serum MMP-7 in a series of patients with advanced bladder cancer." (PMID 25984271, 2014). "Multivariate analysis identified high MMP-7 serum concentration as an independent prognostic factor for survival in patients with advanced bladder cancer (R?=?2.1, 95% CI, 1.1 to 4.4)." (PMID 25984271, 2014). "Recently, several genes have been identified that are associated with bladder cancer progression and poor prognosis, such as excision repair cross-complementing group 1 (ERCC1), matrix metalloproteinase-7 (MMP-7), hyaluronidase 1 (Hyal-1)." (PMID 24223213, 2013). "Interestingly, despite the lack of differences between the study and control group in the urine level of MMP-7, fourfold elevated MMP-7 concentration in urine was detected in patients with bladder cancer with regional or distant metastasis." (PMID 33923108, 2021). "Therefore, tissue and circulating MMP-7 levels were evaluated in 124 bladder cancer patients who received postoperative platinum-based chemotherapy." (PMID 33396213, 2020). "In the present study, we measured MMP-7 serum levels particularly in patients with advanced bladder cancer and analyzed their correlation with clinical parameters to determine whether serum MMP-7 could also be used as a prognostic marker." (PMID 25984271, 2014). "The aim of this study was to analyze the prognostic value of MMP-7 serum level particularly in advanced bladder cancer by quantifying MMP-7 concentration (using a sandwich fluoroimmunoassay) in serum samples from 56 patients with locally advanced or metastatic disease at time of MMP-7 analysis." (PMID 25984271, 2014). "In urinary bladder cancer (UBC), serum MMP7 levels discriminate patients with metastases, wherein MMP7 is 2.9-fold higher in samples of patients with node-positive compared with node-negative tumors." (PMID 30678058, 2019).
bladder cancer (continued). "Urinary MMP-9 levels, serum MMP-7 levels, and tissue levels of MMP-2, MMP-7, and MMP-14 have been identified as prognostic markers of bladder cancer." (PMID 22852097, 2012). "In addition, endostatin, the generation of which is strictly related to MMP-7, is a prognostic marker—high serum levels correlate significantly with unfavorable DSS and DMFS in bladder cancer patients." (PMID 30678058, 2019). "Elevated MMP-7 concentration was detected in urine samples from patients with regional or distant metastasis in comparison to patients with localized disease and controls, suggesting that MMP-7 could be a putative biomarker for the diagnosis and monitoring of bladder cancer." (PMID 25984271, 2014).
metastatic disease (15 papers, 2012 to 2025). "The first study from 2010 on UBC demonstrated in a German patient cohort that elevated tissue expressions and serum concentrations of MMP-7 were associated with the presence of LNs and distant metastatic disease." (PMID 37175566, 2023). "Perlecan is highly expressed in the bone marrow reticular matrix and reports show that higher MMP-7 serum concentrations are associated with metastatic disease and are predictive of poor prognosis." (PMID 26862737, 2016). "Elevated serum MMP-7 levels in human patients with PDAC correlated with metastatic disease and decreased survival." (PMID 33918254, 2021). "Notably, MMP14 remained consistently expressed in both primary and metastatic tumors, while MMP7 and MMP11 were predominantly expressed in the earlier stages." (PMID 40604111, 2025). "Moreover, MMP‐7 levels correlated with more advanced, metastatic disease and the combination of MMP‐7 and SDC1 demonstrated prognostic value in PDAC." (PMID 39263943, 2024). "While MMP-7 inhibitors previously failed in clinical trials for treatment of metastatic disease, the findings reported here point to new avenues to interfere with downstream activation of dyscohesion and migration resulting from MMP-7 cleavage of the PSPN Complex." (PMID 33809984, 2021). "Furthermore, increased circulating levels of MMP-7 have been correlated with metastatic disease and poor patients¿ survival in colorectal, ovarian and renal cancer." (PMID 25984271, 2014). "Downstream targets of β-catenin signaling include MMP-7, which is involved in CRC metastatic disease progression." (PMID 23675573, 2013). "Therefore, MMP-7 can potentially be utilized for the site-specific release of anti-metastatic drugs against human CRC primary and metastatic tumors." (PMID 36831488, 2023). "In this work, we assessed the ability of MMP-7 to digest all components of the PSPN Complex in the context of PCa, a metastatic disease with proclivity to metastasize to the perlecan-rich bone marrow where it further metastasizes by production of circulating tumor cells (CTCs)." (PMID 33809984, 2021). "To investigate whether MMP-2 and MMP-7 were up-regulated by ATF4 in vivo, we performed immunohistochemistry in the metastatic tumors that had been injected with the TE-1LM-ATF4, TE-1HM-SCR, and TE-1HM-siATF4 cells." (PMID 25078779, 2014). "In addition, three mice with metastatic tumors showed higher serum MMP7 levels (112.13 ± 22.30 pg/ml; n = 3) than the nonmetastatic PANC1 tumor-bearing mice (81.98 ± 10.87 pg/ml; n = 7; P < 0.05)." (PMID 35659367, 2022). "MMP7, MMP13, and MMP10 were upregulated, and MMP12 and MMP9 were downregulated in metastatic tumours compared with nonmetastatic tumours." (PMID 31996191, 2020). "MMP7, MMP13, and MMP10 were upregulated in metastatic tumours compared with nonmetastatic tumours." (PMID 31996191, 2020).
oral squamous cell carcinoma (14 papers, 2014 to 2025). "GAD1 plays a crucial role and has been identified as a potential target for oral squamous cell carcinoma, due to its interaction with the Wnt/β-catenin/MMP7 pathway." (PMID 36814556, 2023). "Autoantibodies against matrix metalloproteinase-7 (MMP-7), a member of the matrix metalloproteinase family, were also found in many cancers, including esophageal and oral squamous cell carcinoma." (PMID 34336006, 2021). "In oral squamous cell carcinoma, IL-8 was reported to up-regulate the production of MMP-7 via the IL-8 receptor β." (PMID 33396653, 2020). "We found that increased levels of SIRT1 in oral squamous cell carcinoma tissue contributing to decreased Smad4 acetylation and repressed MMP7 activity." (PMID 25424420, 2014). "In this study, we demonstrated that SIRT1 suppresses the EMT process in oral squamous cell carcinoma cells by deacetylating Smad4 and repressing MMP7 expression." (PMID 25424420, 2014). "Only one study indicated that the MMP-7 autoantibody might be a novel prognostic biomarker for oral squamous cell carcinoma." (PMID 34336006, 2021). "However, there is a paucity of data regarding the value of anti-MMP7 Abs as prognostic and/or predictive biomarkers in cancer patients; only one study in patients with oral squamous-cell carcinoma identified anti-MMP7 Abs to be an independent predictor of poor OS." (PMID 40768895, 2025). "In human oral squamous cell carcinoma (OSCC), SIPA1 interacting with BRD4 increases the level of matrix metalloproteinase 7 (MMP7), leading to increased invasiveness of the OSCC cells and worse prognosis for OSCC patients." (PMID 33917539, 2021). "Moreover, the conserved LEF1 recognition site is present on the promoter region of MMP-7 and is bound directly by LEF1 in oral squamous cell carcinoma cell lines and human oral squamous cell carcinoma tissues." (PMID 28757546, 2017).
breast tumor (13 papers, 2007 to 2023). "It was showed that MMP-7 is aberrantly expressed in human breast tumours, and that elimination of MMP-7 is associated with low invasiveness and slow tumour growth." (PMID 17848954, 2007). "It was shown that MMP-7 is aberrantly expressed in human breast tumours and that elimination of MMP-7 is associated with low invasiveness and slow tumour growth." (PMID 17342087, 2007). "In datasets of primary breast tumors, high expression levels of a subset of MMPs, including MMP7 and MMP14, are correlated to poor prognosis and decreased survival rates." (PMID 35719919, 2022). "Delphinidin can also reduce the expression level of MMP-7 in breast tumor tissues." (PMID 35990843, 2022). "Moreover, MMP-7 may be introduced as a breast tumour biomarker, particularly in the diagnosis of early-stage BC." (PMID 33916127, 2021). "Matrix Metalloproteinase-7 (MMP-7) belongs to a class of zinc-dependent, extracellular proteases that are overexpressed on the surface of breast tumor cells." (PMID 33777893, 2021). "Our data demonstrated MMP-7 activation in human epithelial cells after treatment with IL-1β or TNFα and are supported by publications showing that MMP-7 is secreted by colon and breast tumors, which are primarily epithelial cells." (PMID 36275703, 2022). "For example, aberrant STAT3 signaling promotes breast tumor progression through deregulation of the expression of downstream target genes, which control proliferation (Bcl-2, Bcl-xL, survivin, cyclin D1, c-Myc, and Mcl-1), angiogenesis (Hif1α and VEGF), and EMT (vimentin, Twist, MMP-9, and MMP-7)." (PMID 36446524, 2023).